TTR (transthyretin)
Diseases named in the same sentence as TTR in open-access papers (continued):
Sharing a sentence is not in itself a finding about the gene and the disease.
amyloidosis (continued). "The first documented liver transplant for transthyretin amyloidosis was performed in 1990 with the purpose of removing the organ that had been producing this abnormal protein." (PMID 38275473, 2024). "Transthyretin (TTR) amyloidosis is a progressive disorder characterized by peripheral neuropathy, autonomic dysfunction, and cardiomyopathy." (PMID 39615680, 2024). "While our study is the largest report of patients with TTR amyloidosis to date in Brazil we only access patients in state of São Paulo, the biggest state in Brazil with 44 million inhabitants." (PMID 39033298, 2024). "The late onset of TTR-amyloidosis indicates that one or more additional factors control the misfolding and accumulation of TTR in vivo." (PMID 39615680, 2024). "Inotersen, utilizing the Gapmer structure to target transthyretin (TTR) mRNA for the treatment of hereditary transthyretin (hATTR)-mediated amyloidosis, was successfully developed and approved by the FDA in 2018202." (PMID 38665220, 2024). "Kappa or lambda light chain amyloidosis (ALκ or ALλ), transthyretin (ATTR) and Serum amyloid A-1 (AA) amyloidosis are the four most commonly known amyloidosis subtypes." (PMID 38961380, 2024). "In recent years, the criteria for liver transplantation have become more selective, and the new potential drugs (gene silencers and kinetic stabilizers) have the potential to start a new era in the treatment of transthyretin amyloidosis." (PMID 38275473, 2024). "“ATTRv” (variant) is preferred over “ATTRm” (mutant) to describe hereditary transthyretin amyloidosis, while “ATTRwt” refers to wild-type transthyretin amyloidosis." (PMID 39597824, 2024). "Amyloidosis is a group of protein misfolding diseases, which include spongiform encephalopathies, Alzheimer’s disease and transthyretin (TTR) amyloidosis; all of them are characterized by extracellular deposits of an insoluble fibrillar protein." (PMID 38398647, 2024). "As the awareness of TTR amyloidosis grows, we are more likely to find TTR amyloid deposition outside of the heart and the nervous system and the need to address this gap in literature will escalate." (PMID 38576771, 2024). "One of the first successful RNA-based therapies, patisiran (an siRNA drug), received FDA approval in 2018 for the treatment of hereditary transthyretin-mediated amyloidosis." (PMID 39598489, 2024). "A notable example is the development and clinical application of siRNA-based drugs such as patisiran (Onpattro) and vutrisiran (Amvuttra) for the treatment of hereditary transthyretin-mediated amyloidosis." (PMID 39596348, 2024). "A promising approach to ameliorate transthyretin (TTR) amyloidosis is based on the so-called TTR kinetic stabilizers." (PMID 38398647, 2024). "In 2018, DLin-MC3-DMA (MC3) LNPs, a type of ionizable lipid, were approved by the Food and Drug Administration (FDA) for siRNA delivery to hepatocytes for treating transthyretin (TTR)-induced amyloidosis." (PMID 39329989, 2024). "Hereditary amyloidosis comprises more than 30 subtypes, including TTR, ApoA-I, ApoA-II, gelsolin, lysozyme amyloidosis, cystatin C amyloidosis (ACys), fibrinogen Aα-chain, β2-microglobulin, ApoC2-II, and ApoC39." (PMID 39152105, 2024). "A seminal study explored the use of LNP-mediated liver delivery of a siRNA targeted to treat transthyretin (TTR)-induced amyloidosis and was the first LNP-siRNA drug to achieve marketing approval in 2018." (PMID 39000440, 2024). "Ten studies also analyzed the effect of treatment with a TTR-stabilizer or TTR-gene silencer which was given to retard or halt the disease progression of the amyloidosis." (PMID 38612579, 2024). "The Fx-005 trial focused on transthyretin amyloidosis patients with polyneuropathy, and the Val30Met in the TTR variant was a multinational, multicenter, randomized, double-blinded, and placebo-controlled study." (PMID 39286810, 2024).
amyloidosis (continued). "A similar explanation can be suggested regarding the vitreous body of the eye, which also is a characteristic site of TTR-amyloidosis and where the overall protein concentration is low." (PMID 39615680, 2024). "Amyloid transthyretin (ATTR) amyloidosis is one of the most common types of amyloidosis and is characterized by the accumulation of full-length and fragmented monomers of TTR in tissues." (PMID 38233673, 2024). "Bone scintigraphy is key to non-invasively diagnosing wild-type transthyretin (ATTRwt) amyloidosis, and is mainly used to assess cardiac radiotracer uptake." (PMID 39115713, 2024). "Amyloidosis affecting the heart are predominantly of the transthyretin type (acquired in the older or genetic in the younger patients), and the monoclonal immunoglobulin light chain (AL) type which is solely acquired." (PMID 38682372, 2024). "The most common forms of amyloidosis with cardiac involvement are light chain (AL) and transthyretin (ATTR) amyloidosis." (PMID 39407933, 2024). "Wild-type transthyretin amyloidosis (ATTRwt) is an age-dependent form of systemic amyloidosis characterized by the deposition of amyloid fibrils comprising the transthyretin (TTR) protein in the heart." (PMID 38888709, 2024). "This supports the need to increase awareness regarding the range of outcomes associated with TTR mutations across worldwide populations to reduce misdiagnosis and delayed diagnosis of TTR-related amyloidosis." (PMID 38523305, 2024). "Another pivotal avenue in managing ATTR-amyloidosis focuses on silencers, strategically designed to address the root cause of the condition by reducing the production of TTR-protein." (PMID 38809394, 2024). "After weighing the potential risks and benefits, off-label treatment with diflunisal to slow down the progression of TTR amyloidosis was considered, but ultimately deferred." (PMID 38576771, 2024). "A newly launched study, “Hereditary transthyretin-related amyloidosis and longitudinal monitoring of TTR-positive patients” (TRAMmoniTTR), is a continuation and expansion of the preceding TRAM epidemiological analysis." (PMID 39458146, 2024). "Transthyretin (ATTR) amyloidosis and immunoglobulin light chain (AL) amyloidosis are the two main types of systemic amyloidosis that can affect the nervous system." (PMID 38612579, 2024). "Overall, the success of patisiran in treating transthyretin amyloidosis underscores the potential of siRNA-based gene silencing as a transformative approach to tackling rare genetic diseases." (PMID 39598489, 2024). "With the growing repertoire of recently developed drugs to treat TTR-related amyloidosis, a significant health disparity exists for undiagnosed patients." (PMID 38541013, 2024). "The disease can be both inherited and acquired, with the inherited form (ATTRv amyloidosis) linked to mutations in the TTR gene, and the acquired form (ATTR wt amyloidosis) associated with amyloid derived from the native protein sequence." (PMID 39615680, 2024). "Cardiac amyloidosis was confirmed in 12 patients (16.2%): 6 with transthyretin (TTR) amyloidosis, 5 with light-chain (AL) amyloidosis, and 1 with renal amyloidosis." (PMID 39330320, 2024). "This therapy involves the administration of LNP-encapsulated mRNA encoding cas9 protein and gRNA targeting misfolded transthyretin (TTR), a protein predominantly accumulated in the heart and nerves of transthyretin amyloidosis patients." (PMID 38486748, 2024). "Eplontersen silences the TTR mRNA and suppresses the translation and misfolded protein, thus reducing the amyloidosis." (PMID 38399458, 2024). "TTR genetic testing should be offered to patients with clinical suspicion of amyloidosis and a family history of CM or PNP." (PMID 39458146, 2024). "Transthyretin (TTR) amyloidosis (abbreviated ATTR amyloidosis) is a life-threatening disease caused by the accumulation of misfolded TTR proteins in tissues, particularly in the heart and nerves." (PMID 39543114, 2024).
amyloidosis (continued). "In a high percentage of AS patients (16%) the presence of transthyretin (TTR) amyloidosis within the myocardium has been reported." (PMID 38256243, 2024). "Amyloidosis of the diffuse alveolar-septal type was tentatively diagnosed, and immunostaining for amyloid A, kappa, lambda, beta two-microglobulin, and transthyretin was performed to ascertain the type of amyloidosis." (PMID 39759624, 2024). "The definitive diagnosis of mutant transthyretin amyloidosis requires evidence of amyloid deposits from a biopsy, as well as a minimum of two symptoms associated with amyloidosis." (PMID 38893695, 2024). "The main objective of this study is to perform a descriptive observational analysis on the presentation of transthyretin amyloidosis in families carrying the p.Ser43Asn gene of the identified index case." (PMID 39449414, 2024). "Persistently elevated Tn levels are frequently found in amyloidosis, including both primary/light chain (AL) and transthyretin (TTR) amyloidosis." (PMID 38472975, 2024). "The objective of this article is to perform a descriptive analysis on the presentation of transthyretin amyloidosis in families carrying the p.Ser43Asn gene based on the index case identified in the period from January 2020 to January 2022." (PMID 39449414, 2024). "With the development of disease-modifying therapies such as TTR stabilizers and gene silencing agents, early detection of ATTRv amyloidosis has become more critical than ever." (PMID 39639351, 2024). "The amyloidosis group included five transthyretin samples and four AL amyloidosis cases [κ (n = 1) and λ (n = 3)]." (PMID 39273305, 2024). "In the Transthyretin Amyloidosis Outcomes Survey (THAOS) registry, over 30 different pathogenic TTR variants were reported, the most common being Val122Ile (45%), Thr60Ala (20%), and Val30Met (6%)." (PMID 39685666, 2024). "Amvuttra was approved by the FDA and EMA in 2022 to treat polyneuropathy of hereditary transthyretin-mediated amyloidosis in adults." (PMID 39285061, 2024). "In contrast, ATTRwt amyloidosis is ‘acquired’ and results from the accumulation of the ‘wild-type’ TTR protein." (PMID 39458146, 2024). "Hereditary transthyretin (ATTRv) amyloidosis is a progressive disease characterized by the extracellular deposition of transthyretin (TTR)-derived amyloid fibrils in various organs and tissues." (PMID 37843599, 2024). "Vutrisiran, approved in June 2022, is like patisiran for the therapy of transthyretin amyloidosis peripheral neuropathy and targeted to the transthyretin mRNA." (PMID 38668084, 2024). "TTR-amyloidosis is today also treated by downregulating the liver-specific expression of TTR, using RNA interference and antisense oligonucleotides." (PMID 39615680, 2024). "The field has seen notable successes, such as approved treatments for spinal muscular atrophy and hereditary transthyretin-mediated amyloidosis." (PMID 39596348, 2024). "The FDA-approved two siRNA therapeutic products are Givosiran, which targets ALAS1 to treat AHP, and Patisiran, which targets polyneuropathy to treat hereditary transthyretin-mediated amyloidosis." (PMID 37238946, 2023). "TTR in TTR amyloidosis is a particularly interestingtarget due to its abundance of accessible blood samples and numeroussuccessful available treatments." (PMID 37477604, 2023). "In transthyretin (ATTR) amyloidosis, amyloid is derived from the protein transthyretin and deposits frequently occur in the heart, leading to ATTR cardiomyopathy (ATTR-CM)." (PMID 37561144, 2023). "Extracellular insoluble deposits of TTR in several human organs give rise to distinct progressive and fatal clinical syndromes known as TTR amyloidosis." (PMID 37401663, 2023). "Another example came from transthyretin amyloidosis, a life-threatening disease stemmed from progressive accumulation of misfolded transthyretin (TTR) protein that mainly produced by the liver." (PMID 37027099, 2023).
amyloidosis (continued). "Patisiran, binding transthyretin (TTR) mRNA, has demonstrated an ability to improve heart failure and polyneuropathy in patients with TTR amyloidosis, even in older patients with wild-type form." (PMID 38203499, 2023). "This year, vutrisiran (AmvuttraTM) received the green light for the treatment of the polyneuropathy of hereditary transthyretin-mediated amyloidosis in adults." (PMID 36770706, 2023). "Patisiran was the first therapy based on FDA-approved short-interfering RNA (Si-RNA) technology and acts by reducing the production of mutant and wild-type transthyretin, thus improving the multiple clinical manifestations of hATTR amyloidosis." (PMID 37046940, 2023). "The continuous accumulation of transthyretin (TTR) protein in hATTR amyloidosis patients can lead to movement disorders." (PMID 36843103, 2023). "Various types of amyloidosis can affect the heart, but the two most common types are dominant: amyloid transthyretin (ATTR) amyloidosis and amyloid immunoglobulin light-chain (AL) amyloidosis." (PMID 37460984, 2023). "The AMY-CCM Registry, which has just begun, will evaluate the efficacy of CCM in patients with HF and diagnosed TTR amyloidosis to bring new evidence on its potential impact as a therapeutic option." (PMID 36769832, 2023). "Based on the results of immunohistochemical amyloid typing, amyloid A (AA) amyloidosis was detected in 23%, amyloid light chain (AL) lambda in 32%, AL kappa–in 9%, and transthyretin (ATTR) amyloidosis–in 36% of observations." (PMID 37893183, 2023). "In 2018, the first siRNA drug, Onpattro (Patisiran), was approved by FDA for the treatment of hereditary transthyretin (TTR)-mediated amyloidosis." (PMID 37649616, 2023). "Progressive amyloid deposition in the heart is the main mechanism of damage in ATTR-CM amyloidosis, whereas the toxic effect of TTR oligomeric species seems to be less relevant." (PMID 37111614, 2023). "The occurrence of cloudy areas in the vitreous due to hereditary amyloid transthyretin (ATTRv) amyloidosis can range from 5.4% to 35%." (PMID 37622058, 2023). "Familial transthyretin amyloidosis (FTA) is a rare and severe autosomal dominant disease that is caused by a mutation in the transthyretin (TTR) gene." (PMID 37589912, 2023). "Hereditary and wild-type transthyretin-mediated (ATTRv and ATTRwt) amyloidoses result from the misfolding of transthyretin and aggregation of amyloid plaques in multiple organ systems." (PMID 37740174, 2023). "The first clinical trial involving systemic delivery of CRISPR components used SpCas9 and a sgRNA targeting TTR to reduce the production of misfolded transthyretin protein in hereditary transthyretin amyloidosis." (PMID 36873375, 2023). "Following an amyloidosis diagnosis, testing the TTR gene is mandatory for the patients and their adult relatives, regardless of age or diphosphonate scintigraphy results." (PMID 37901600, 2023). "The nanoparticle-based siRNA formulation, known as Patisiran (ONPATTROTM) targets transthyretin mRNA and is used for the treatment of polyneuropathy in a hereditary form of transthyretin-mediated (hATTR) amyloidosis." (PMID 36814718, 2023). "There are published cases of transthyretin amyloidosis diagnosed only at autopsy in elderly patients who died from the novel coronavirus disease." (PMID 37893183, 2023). "In brain, TTR it is related to development of Alzheimer’s disease or Amyloidosis but serum TTR has also been shown to correlate to prognosis and need for rehabilitation after ischemic stroke." (PMID 37420193, 2023). "ATTR amyloidosis stems from a misfolded TTR protein; ATTRwt amyloidosis is age-related and predominantly affects men > 70 years old, while the clinical manifestations of ATTRv are strongly related to the specific genetic variants." (PMID 37892778, 2023). "Transthyretin (ATTR) amyloidosis is a progressive protein misfolding disease with frequent cardiac involvement." (PMID 37561144, 2023).
amyloidosis (continued). "Amyloidoses can affect several organs, for example, transthyretin amyloidosis, or are limited to a single organ, such as the brain in AD." (PMID 36830892, 2023). "Patisiran silences transthyretin mRNA in the liver and decreases serum levels of the protein, thus reducing the amyloid deposits." (PMID 37728251, 2023). "TTR misfolding can lead to two distinct forms of amyloidosis: hereditary (ATTRv) and wild-type (ATTRwt)." (PMID 37124609, 2023). "In other fields of medicine including neurology, silencing of transthyretin (TTR) was evaluated for the treatment of TTR amyloidosis." (PMID 37998395, 2023). "It has been reported two types of transthyretin (TTR) amyloidosis in cardiac tissue of aged individuals: wild-type transthyretin (wtTTR), also known as senile cardiac amyloidosis and mutant or hereditary amyloidosis (mTTR)." (PMID 37163425, 2023). "The field received its major breakthrough in 2018 with the approval of the first siRNA-based drug ‘Patisiran’ (Onpattro®) for the treatment of transthyretin-mediated amyloidosis." (PMID 36814718, 2023). "A CRISPR–Cas9 in vivo gene editing approach for transthyretin amyloidosis is also being investigated in a clinical trial (funded by Intellia Therapeutics and Regeneron Pharmaceuticals; ClinicalTrials.gov number, NCT04601051)." (PMID 36768539, 2023). "Some interesting evidence has also suggested a possible direct interaction between omega-3 fatty acids and proteins that are involved in neurodegenerative processes, i.e., β-amyloid for AD, α-synuclein in PD, and transthyretin (TTR) in TTR amyloidosis (ATTR)." (PMID 36771455, 2023). "There is evidence that TTR inactivation is effective in people, as therapy with siRNA or ASOs targeting TTR decreased the development of hATTR amyloidosis with polyneuropathy." (PMID 36851119, 2023). "Studies report that PUFAs have a role in contrasting neurodegenerative processes related to amyloidogenic proteins, such as β-amyloid for AD, α-synuclein in PD, and transthyretin (TTR) in TTR amyloidosis." (PMID 36771455, 2023). "Transthyretin (TTR) amyloidosis is a systemic disease characterized by the deposition of insoluble wildtype or mutant TTR fibrils in several tissues." (PMID 37953763, 2023). "In 2018, ONPATTRO®, an LNP that contained a siRNA (siRNA-LNP) against transthyretin, was approved as the first siRNA therapeutic technology for the treatment of hereditary transthyretin-mediated amyloidosis." (PMID 37514007, 2023). "The diagnosis of amyloidosis was confirmed with multimodality imaging in the early stage, which helped to start specific medicamental treatment with the transthyretin stabilizer tafamidis." (PMID 36837536, 2023). "Patisiran, the first FDA-approved siRNA drug, is delivered to the liver by LNPs to cure transthyretin-mediated amyloidosis (ATTR)." (PMID 37430086, 2023). "Transthyretin (ATTR) amyloidosis is responsible for the majority of cardiac amyloidosis (CA) cases and can be reliably diagnosed with bone scintigraphy and the visual Perugini score." (PMID 35562639, 2023). "Transthyretin (TTR), a vitamin A and thyroxin carrier protein which is produced mostly by the liver, is the amyloid precursor of patients with late onset wild-type amyloidosis (ATTRwt) as well as patients with variant-/hereditary-type amyloidosis (ATTRv)." (PMID 36902083, 2023). "A diet enriched with nutraceuticals, as supplements, is a potentially powerful tool to prevent or postpone the TTR misfolding process and amyloidosis." (PMID 36771455, 2023). "To fill this gap in knowledge, we promoted an observational registry whose primary aim is to evaluate the efficacy of CCM in patients with HF and diagnosed TTR amyloidosis." (PMID 36769832, 2023).